KDM6A (lysine demethylase 6A)
Diseases named in the same sentence as KDM6A in open-access papers (continued):
Sharing a sentence is not in itself a finding about the gene and the disease.
tumor (continued). "Moreover, the demethylase KDM6A (also called UTX) and the histone methyltransferases mixed lineage leukaemia, MLL2 (KMT2D) and MLL3 (KMT2C), display inactivating and truncating mutations, suggesting tumour suppressive functions." (PMID 29759978, 2018). "Similarly, KDM6A appears to also have both tumor suppressive and oncogenic activities." (PMID 28968467, 2017). "The fact that KDM6A has been classified as a putative tumor suppressor may support the model that KDM6A may also be induced as a consequence of E7 triggering a cell intrinsic tumor suppressive defense response." (PMID 23673719, 2013). "The epigenetic modifier lysine demethylases KDM6A (UTX), which escapes X-chromosome inactivation, is expressed at higher levels in females.In T-ALL KDM6A has been identified as a tumor suppressor." (PMID 41562928, 2026). "KDM6A promotes AML progression and drug resistance through its tumor suppressor functions and involvement in DNA repair mechanisms." (PMID 40647534, 2025). "This review will therefore focus specifically on PDAC, highlighting the significant, but less-understood roles of tumour suppressors, such as PTEN, KDM6A, and ARID1A in PDAC." (PMID 40723241, 2025). "Depending on tumor type, KDM6A (UTX) can either promote or suppress tumorigenesis, but it is usually considered as anti-neoplastic." (PMID 40940894, 2025). "KDM6A exerts its anti-tumor effects through the epigenetic activation of RHGDIB transcription, which suppresses Rac1—a key regulator of tumor cell motility, invasiveness, and metastasis." (PMID 40600050, 2025). "The cell-type-specific (defined based on marker gene expression profiles and clustering analysis) expression of CD44, FGF2, FGF10, KDM6A, FN1, and MMP2 in the tumor microenvironment of UCEC was analyzed using the TISCH2 database." (PMID 39833941, 2025). "In subcutaneous xenograft mice, KDM6A depletion significantly promoted tumor growth, and treatment with the IGF1 neutralization antibody reduced this tumor-promotion effect." (PMID 40659611, 2025). "Interestingly, we observed the loss of histone lysine demethylases KDM5C and KDM6A in NATs but not in tumor tissues, suggesting that the absence of these enzymes might be linked to the initiation of BTC development." (PMID 41301905, 2025). "In contrast, CisR tumor spheroids maintained the expression of CREB and its downstream targets TNKS and KDM6A, as well as cell survival in response to cisplatin." (PMID 40860181, 2025). "EZH2 has been involved in the tumor progression mechanisms of a variety of cancer types, whereas KDM6A and KDM6B have been identified in numerous malignancies with either oncogenic or tumor suppressor roles." (PMID 41085408, 2025). "GSK-J4, developed as a specific inhibitor of KDM6A/B to enhance H3K27 methylation, has demonstrated anti-cancer abilities by reducing tumor cell proliferation and inducing apoptosis in various studies." (PMID 38539453, 2024). "Genetic and pharmacologic inhibition of polycomb H3K27me3 demethylases KDM6A and KDM6B sensitized cisplatin-resistant and wild-type TGCT cells to cisplatin and produced dramatic synergistic tumor regression in animal models." (PMID 39483904, 2024). "Genetic and pharmacologic inhibition of KDM6A and KDM6B sensitized cisplatin-resistant and wild-type TGCT cells to cisplatin and produced dramatic synergistic tumor regression in animal models." (PMID 39482699, 2024). "KDM6A activates the IFN-γ pathway, facilitating immune-regulatory cell recruitment and enhancing anti-tumor immune responses." (PMID 39731171, 2024). "Four target sequences had been previously detected in tumor DNA by standard-of-care (SNVs in either the CTNNB1, SMO, or KDM6A genes)." (PMID 37046633, 2023). "The xenograft tumour model and HCC cell lines were used to evaluate the role of KDM6A in HCC drug sensitivity to lenvatinib." (PMID 37846441, 2023). "Like KDM6A, KDM6B is highly expressed in various cancers and is conducive to tumor development and drug resistance." (PMID 36797239, 2023).
tumor (continued). "It has also been found that tumor driver genes IDH1/2, JARID1C/KDM5C and UTX/KDM6A can regulate histone demethylation and thus affect cancer metabolism and tumor progression." (PMID 36941564, 2023). "KDM6A and RBM10 were more likely to have SNV in tumours derived of older patients in TCGA and AACR GENIE but were not recurrently mutated in PCAWG data and not analysed in that dataset." (PMID 35017538, 2022). "The well-documented immunomodulatory effect of GSK-J4 in inflammatory conditions suggests that KDM6A/B inhibition could alter the immune microenvironment of solid tumours in favour of an anti-inflammatory, tolerogenic milieu, possibly promoting immune evasion by tumour cells." (PMID 35915507, 2022). "Inactivating mutations in ccRCC are also found in two histone demethylases known to be tumour suppressors: KDM5C (demethylates H3K4me3) and KDM6A /UTX." (PMID 35406676, 2022). "For example, it not only acts as tumor suppressor in certain T-ALL cases 32, but KDM6A overexpression in TAL1-expressing T-ALL increasesd their growth." (PMID 33456567, 2021). "This present study demonstrates that KDM6A and MMR can be used as tumor biomarkers for CRC prognosis to analyze different grouped samples from The Cancer Genome Atlas (TCGA)." (PMID 33174323, 2021). "Treatment dramatically decreased the tumor burden in KDM6A WT AML-491 bearing mice compared to control (P = 0.0157), whereas only a modest drop in tumor burden was observed in treated AML-393 bearing mice." (PMID 31201358, 2020). "KDM6A and KDM5C are two of several putative tumor suppressors on the X-chromosome proposed to contribute to decreased cancer risk in females." (PMID 32295632, 2020). "The most prominent of these are candidate tumour suppressors; KDM6A (lysine demethylase 6 A), DDX3X (dead-box RNA helicase 3) and UBA1." (PMID 31772231, 2019). "We have reviewed the most recent findings regarding cancer-specific metabolic reprogramming and the tumor-suppressive roles of JARID1C/KDM5C and UTX/KDM6A." (PMID 31221981, 2019). "Although tumour hypoxia is strongly associated with cancer progression and resistance to therapy, we cannot conclude whether in SPN mutation or reduced expression of KDM6A is an epiphenomenon of oxygen shortage or instead precedes the formation of a hypoxic microenvironment." (PMID 30306561, 2019). "In contrast, significant effects on gene expression were observed in tumor cell lines with likely suboptimal levels of functional UTX, such as RT112 and VM-CUB-1, and upon reintroduction of UTX into SW-1710 KDM6A knockout cells." (PMID 30987376, 2019). "KDM6A and UTY have significant tumor suppressor activity in several types of cancer." (PMID 40949882, 2025). "Importantly, the inhibition of KDM6A and KMT2B reduced tumor growth and prevented recurrence in xenografted animals." (PMID 40940894, 2025). "KDM6A encodes K demethylase 6A, also known as ubiquitously transcribed tetratricopeptide repeat, X chromosome (UTX), which catalyzes the removal of trimethyl groups from histone 3 lysine 27 (H3K27) (as illustrated in the graphical abstract) and acts as a tumor suppressor." (PMID 41244070, 2025). "KDM6A, a member of the COMPASS-like complex, possesses demethylase activity that counteracts the PRC2 complex by demethylating H3K27me3 and facilitating H3K4me, thereby enhancing IFN responses and tumor-suppressive gene expression." (PMID 40650108, 2025). "The mutations in the chromatin modifier genes KDM6A and KMT2D displayed low AFs (0.02, 0.01, respectively), suggesting minimal impact on tumor biology especially as they were not carried into the metastatic lesions." (PMID 39349591, 2024). "While KDM6A and KDM6B have a tumor suppressor role, other members of the KDM family like KDM2B, KDM3A, and KDM5A may serve as oncogenes in PDAC." (PMID 38791111, 2024).
tumor (continued). "While normally regulating cell differentiation, the absence of functional KDM6A promotes the mesenchymal identity of cancer cells, facilitating tumor growth and metastasis, thereby exacerbating PDAC aggressiveness." (PMID 38791111, 2024). "The dramatic in vivo effects, as compared to in vitro effects of GSK-J4 and KDM6A/KDM6B-knockdown, suggest that host and/or tumor microenvironment contributions may be occurring during cisplatin sensitization." (PMID 39482699, 2024). "As KDM6A inhibition seems to be well tolerated in mice, it could potentially be used in patients with TNBC who have KMT2C or KMT2D mutant tumours, in combination with currently used therapies." (PMID 38926506, 2024). "It has been demonstrated that KDM6A is frequently inactivated in PDAC, suggesting that it may play a tumor-suppressive role." (PMID 38791111, 2024). "The X-escapee KDM6A opposes EZH2 function and can act as a tumor suppressor." (PMID 38949020, 2024). "One landmark study demonstrated six tumour-suppressor genes that escape XCI and may contribute to cancer sex-disparity (ATRX, CNKSR2, DDX3X, KDM5C, KDM6A, and MAGEC3)." (PMID 37759468, 2023). "Of note, the tumour suppressors KDM5C and KDM6A have been previously identified to play fundamental roles in cancer sex-disparity, as they escape XCI to retain their function when mutated, while ZRSR2 mutations/loss have been associated with sex-disparity in blood cancers." (PMID 37759468, 2023). "Mutations in KDM6A and ARID1A have been reported as the most frequently altered chromatin modifying genes in human UC regardless of tumor stage or grade, suggesting that they are early events." (PMID 37079639, 2023). "Using publicly available sequencing data of human tumours, we found that in particular the catalytically active components of the MLL3/MLL4 COMPASS-like complex MLL3, MLL4 and KDM6A show a high alteration frequency that presumably lead to reduced protein expression." (PMID 34509979, 2022). "Her tumor molecular profile performed 2.5 years after completion of treatment with BBI608 demonstrated MYB proto-oncogene (MYB) chromosomal rearrangement, BCL6 corepressor (BCOR) P698fs, and lysine demethylase 6A (KDM6A) R1415 *." (PMID 35267638, 2022). "Finally, it is notable to mention that the role of KDM6A/UTX, an enzyme that catalyzes the demethylation of H3K27me2 and H3K27me3, acts as a tumor suppressor and can interact with other epigenetic elements." (PMID 34072826, 2021). "This outcome can explain, at least in part, why KDM6A inhibits T24 tumour growth in vivo but does not affect the monolayer growth of T24 cells in vitro." (PMID 34006303, 2021). "If ablation of KDM6A or KDM6B increases cancer cell metastasis, GSK-J4 treatment might result in increased tumor growth instead." (PMID 34950587, 2021). "Lysine-specific demethylase 6A (KDM6A) is a member of the histone H3 lysine 27 demethylase gene family, which is reported to exert pro-tumorigenic effects in some cancer types but is also considered a tumour suppressor in other contexts." (PMID 34051747, 2021). "Moreover, similar to KDM6A, KDM6B expression is also subjected to different levels of its cosubstrates from cellular metabolism and tumor microenvironments." (PMID 34950587, 2021). "The analysis of molecular signatures in human tumors, and the semblance of mouse genetic phenotypes, suggested that KDM6A and HNF1A might control common tumor‐suppressive programs in pancreatic exocrine cells." (PMID 32154941, 2020).
tumor (continued). "However, in the first set of results, HDM genes (KDM1A, KDM5B, KDM6A and KDM7C) were mostly overexpressed in tumour tissue comparatively to normal oesophageal epithelium." (PMID 32429269, 2020). "Additionally, H3K27me3 demethylase UTX/KDM6 plays crucial roles in GNP differentiation through NEUROD2 expression and recruits immune cells to the tumor microenvironment, thereby UTX/KDM6A deletion contributes to SHH-MB development by maintaining undifferentiated and immunologically cold states." (PMID 40599851, 2025). "Inhibition of the histone demethylases KDM6A and KDM6B by a pharmacological inhibitor, GSKJ4, increased global H3K27me3 in K27M-mutant brainstem gliomas, leading to reduced tumor growth, improved survival, and sensitized tumor cells to radiation therapy in preclinical models." (PMID 40556679, 2025). "Moreover, in CisS tumor spheroids, cisplatin treatment substantially decreased the expression of CREB mRNA and protein, and decreased the levels of TNKS and KDM6A proteins, resulting in a substantial increase in apoptotic cell death." (PMID 40860181, 2025). "However, approximately 15–25% of X-chromosomal genes escape XCI (termed “escape genes”), many of which exhibit higher expression levels in females than males, particularly those involved in immunity and tumor suppression, such as Toll-like receptor 7 (TLR7) and KDM6A." (PMID 41019050, 2025). "Genomic profiling revealed no actionable targets but NOTCH1 and KDM6A frameshift and CTCF splice site mutations (no MYB/L fusion) with a low tumor mutational burden (TMB), microsatellite stable (MSS) and negative programmed death ligand 1 (PD-L1) were observed." (PMID 39451738, 2024). "In addition, using the TCGA cancer RNA-seq dataset and TIMER31, we found that the expression of CD48 and KDM6A was positively correlated with intertumoral NK cell abundance in many human cancer types, suggesting that KDM6A and CD48 affect NK-mediated tumor immunity in a variety of human cancers." (PMID 38355622, 2024). "However, KDM6A mediates tumor suppression and developmental regulation through noncatalytic functions." (PMID 37410700, 2023). "Thus, the X chromosome KDM6A and the Y chromosome KDM6C each may suppress tumor growth and partially compensate for each other in males." (PMID 34768683, 2021). "Strong correlations were noted between mutations in oncogenes and tumor suppressor genes and non-T cell-inflamed tumors with examples including IDH1 and GNAQ as well as less well-known genes including KDM6A, CD11c, and genes with unknown functions." (PMID 33106165, 2020). "KDM6A is not a tumor suppressor in all T-ALL molecular subtypes." (PMID 33003334, 2020). "Nevertheless, one hypothesis that may explain the oncogenic function of KDM6B in T-ALL, versus the tumor suppressive function of KDM6A in T-ALL, could be the lack of N-terminal TPR domain in KDM6B, but the exact cause and mechanism is yet to be explored." (PMID 33003334, 2020). "Additional low-frequency SNVs in KDM6A (in-frame gain of codon, allelic frequency 7%) and XPO1 (splice region variant, allelic frequency 6%) were identified in the PDOX, but not in the patient tumor or the subcutaneous PDX." (PMID 31732509, 2019). "It is not clear whether KDM6A expression also represents a cellular tumor suppressive defense response, how E7 triggers it and what the transcriptional consequences of KDM6A expression may be." (PMID 23673719, 2013). "However, KDM6A escape is not all bad news for women health as this gene is also a tumor suppressor." (PMID 33498655, 2021). "Although KDM6A mutations were not mutually exclusive with any of the posterior HOXA expression patterns, further investigations into differential HOX-gene expression patterns are warranted in light of confounding factors such as tumor heterogeneity and gene functional redundancy." (PMID 25810763, 2015). "As expected tumours showed GFP expression (indicating shRNA expression) and Kdm6a expression was absent in shKdm6a tumour samples." (PMID 34509979, 2022).
tumor (continued). "Moreover, KDM6B, but not KDM6A, regulates RAS/RAF-mediated oncogene-induced senescence (OIS), one of several cell-intrinsic tumor-suppressor responses that function to eliminate aberrantly proliferating, potentially premalignant cells." (PMID 28968467, 2017).